PALB2 (partner and localizer of BRCA2)
Diseases named in the same sentence as PALB2 in open-access papers (continued):
Sharing a sentence is not in itself a finding about the gene and the disease.
breast cancer (continued). "It has been reported that patients with pancreatic cancer carry rare germline deleterious variants of breast cancer susceptibility genes such as BRCA1, BRCA2, PALB2, and ATM." (PMID 38204267, 2025). "Of the 143 patients, 24 (16.8%) had a PGV in a breast cancer susceptibility gene (BRCA1, n = 17; BRCA2, n = 5; PALB2, n = 1; CHEK2, n = 1)." (PMID 39964682, 2025). "In our subgroup analysis of 89 T1N0 breast cancers, 56% of BRCA1-associated cases were TNBC compared to only 18% of BRCA2 and PALB2-associated cases." (PMID 40275390, 2025). "After exclusion of 3 (1.0%) patients with stage IV disease, the final analytic cohort included 309 BRCA1/2 and PALB2-positive women with operable breast cancer; 160 (51.8%) BRCA1, 130 (42.1%) BRCA2, and 19 (6.1%) PALB2 carriers." (PMID 40275390, 2025). "The GEN1 gene is implicated in DNA damage repair, as are several high- or moderate-risk breast cancer susceptibility genes, i.e., BRCA1, BRCA2, PALB2, CHEK2, ATM, and BRIP1." (PMID 40649769, 2025). "Because of the higher prevalence of BRCA2 and other pathogenic germline variants, routine referral for genetic counseling and testing (including BRCA1, BRCA2, PALB2, and others as appropriate) is strongly recommended for all men diagnosed with breast cancer." (PMID 41510417, 2025). "This is compared with the guidance in place at the time of the meeting, which stipulated that individuals with a GPV in BRCA1/BRCA2/PALB2 were only eligible for breast cancer surveillance at age 25–30 years if they reached a 10-year risk of 8% or greater." (PMID 41159931, 2025). "We focused on Polish founder mutations in BRCA1, BRCA2, PALB2, CHEK2, NBN and RECQL (18 alleles), which account for one-half of Polish breast cancer families." (PMID 40770660, 2025). "In the remaining PALB2 affected carriers with HR + HER2- breast cancer, higher 21-gene recurrence scores (similar to that of BRCA2 carriers) have been reported, suggesting that tumor biology and chemotherapy response is likely similar between these groups." (PMID 40275390, 2025). "Overall, 1,710 patients had sporadic breast cancer; the BRCA1/2 double mutation frequency was 1.35% (23/1710), and the BRCA1/2 and PALB2 triple mutation frequency was 0.94% (16/1710)." (PMID 38439896, 2024). "Our study found that PALB2 variants, along with BRCA1/2 variants, were associated with increased breast cancer risk." (PMID 38270937, 2024). "The loss-of-function (LOF) classification of most missense variants in tumor suppressor breast cancer genes BRCA1, BRCA2, PALB2, and RAD51C remains unclassified and confounds clinical actionability." (PMID 39430403, 2024). "In total, 364 patients had early onset breast cancer; the double mutation frequency was 1.65% (6/364), and the BRCA1/2 and PALB2 triple mutation frequency was 1.37% (5/364)." (PMID 38439896, 2024). "Tumor suppressor genes BRCA1, BRCA2, PALB2, and RAD51C play crucial roles in homology-directed recombination DNA repair (HDR) activity, and mutations in these genes have been implicated in breast cancer." (PMID 39430403, 2024). "This economic evaluation estimates the cost-effectiveness of prevention strategies for ovarian and breast cancer among individuals with pathogenic variants in cancer susceptibility genes BRCA1, BRCA2, PALB2, RAD51C, RAD51D, and BRIP1." (PMID 38334999, 2024). "In the absence of BRCA1/2 germline mutations, alterations in other specific homologous recombination (HR) genes, such as PALB2, CHEK2, ATM, and NBN, can lead to an increased risk of breast cancer development." (PMID 39272660, 2024).
breast cancer (continued). "In postmenopausal PALB2 carriers, 10-year contralateral breast cancer incidence appears significantly lower at 5.1%." (PMID 38248108, 2024). "We found that, similar to loss of RAD18, UBC13 and PALB2, loss of RNF168 resulted in an increase in fork stalling in both BRCA1-deficient U2OS cells (Supplementary S4A) and BRCA1-deficient breast cancer MDA-MB-231 cells." (PMID 38943334, 2024). "While BRCA1 and BRCA2 remain the most well-known high-penetrance genes, others, such as ATM, BARD1, CHEK2, PALB2, RAD51C, and RAD51D, are now recognized as conferring moderate to high risk for breast cancer." (PMID 39590369, 2024). "Our results from all-comers population genetic screening confirmed that rare pLOF variants in BRCA1, BRCA2, PALB2, ATM, and CHEK2 confer significant risk to breast cancer in the overall population." (PMID 39669587, 2024). "PALB2 p.Q559R was reported previously in the Italian cohort of breast cancer patients with comparatively higher penetrance, which correlates with our findings for the Pashtun ethnicity." (PMID 38784039, 2024). "Other homologous recombination DNA damage repair (HR-DDR) genes associated with breast cancer risk accounted for 15.9% (13/82) of the carriers, including ATM (n = 2), BARD1 (n = 4), CHEK2 (n = 1), PALB2 (n = 2), RAD51C (n = 1), and RAD51D (n = 3)." (PMID 38893140, 2024). "Specifically, PVs in PALB2, ATM, CHEK2, RAD51C, and RAD51D are associated with increased lifetime breast cancer risk, ranging from 20% to 58%, depending on the defective gene and identified variant, while influenced by family history." (PMID 39001430, 2024). "The Talazoparib Beyond BRCA phase 2 study demonstrated the efficacy of Talazoparib, a PARPi, in advanced breast cancer with germline PALB2 PV/LPV, showing activity within the context of HRD beyond BRCA1/2." (PMID 39796639, 2024). "How cost-effective are ovarian and breast cancer risk reduction strategies among women with pathogenic variants in individual cancer susceptibility genes (ie, BRCA1, BRCA2, PALB2, RAD51C, RAD51D, and BRIP1)?" (PMID 38334999, 2024). "PALB2 PV/LPV, in addition to BRCA1/2, is also considered a high penetrance breast cancer susceptibility gene with an absolute lifetime risk of 44–63%." (PMID 39796639, 2024). "Recent molecular diagnostic studies have identified RECQL as an important breast cancer susceptibility gene, similar to BRCA1, BRCA2, and PALB2." (PMID 38439896, 2024). "Among the 12 male breast cancer patients in our cohort, we identified pathogenic variants in CHEK2 (c.846+1G>C) and PALB2 (c.758dup)." (PMID 39590369, 2024). "Two PALB2 carriers (2/12, 16.7%) have documented family history of breast cancer and/or ovarian cancer." (PMID 38914840, 2024).
breast cancer (continued). "Approximately 2.1–6% of women with breast cancer who undergo genetic testing will carry germline pathogenic variants in BRCA1/2, and 0.2–0.9% are carriers of a pathogenic variant in PALB2." (PMID 38248108, 2024). "Recent comprehensive studies have highlighted that pathogenic variants (PVs) across eight distinct genes, such as ATM, BRCA1, BRCA2, CHEK2, PALB2 (FANCN), RAD51C, and RAD51D, exhibit a substantial correlation with breast cancer risk." (PMID 38397209, 2024). "PALB2 (partner and localizer of BRCA2) is considered a high-risk gene in breast cancer, and it encodes for a protein with tumor suppressor activity." (PMID 38784039, 2024). "The incidence of HRD in germline RAD51C/D was lower than in germline BRCA1/2 or PALB2, especially among breast cancer samples." (PMID 38648056, 2024). "In patients with breast cancer, a high incidence of pathogenic variants of BRCA1 and BRCA2 is observed, as well as other highly mutated genes, such as PALB2, CHEK2, MUTYH, and ATM." (PMID 39335183, 2024). "The study will enrol women, unaffected by cancer, undergoing predictive testing at a familial cancer clinic for a pathogenic variant in a known breast cancer (BC) or ovarian cancer (OC) predisposition gene (BRCA1, BRCA2, PALB2, CHEK2, ATM, RAD51C, RAD51D)." (PMID 39107016, 2024). "Limited data are available regarding the partner and localizer of BRCA2 (PALB2) in Chinese patients with early breast cancer." (PMID 38914840, 2024). "Currently, limited studies have addressed the gene–gene interaction among BRCA1, BRCA, and PALB2 in real-world settings of large-scale breast cancer gene analysis." (PMID 38098088, 2023). "Among the 91 men diagnosed with breast cancer, 12 (P/LP) variants were identified (13%); 7/91 displayed a mutation in BRCA2 and 2/91 in PALB2." (PMID 37444530, 2023). "For the 21 women who met synchronous bilateral breast cancer criterion only, three (14.3%) had a pathogenic variant (one in each BRCA1, PALB2, and RECQL)." (PMID 36544278, 2023). "Clinical trial TBCRC 048 put forward that germline PALB2 or somatic BRCA1/2-mutant breast cancer responds well to PARPi." (PMID 37476378, 2023). "In early-onset breast cancer, concurrent germline variants of BRCA1, BRCA2, PMS2, and PALB2 were reported." (PMID 37628631, 2023). "Based on the mutation frequencies, the magnitude of cancer risk, and the influence on clinical management with mutation carriers, the most important breast cancer susceptibility genes include BRCA1, BRCA2, PALB2, and CHEK2." (PMID 37510234, 2023). "The current analysis aims to evaluate the prevalence of genetic alterations specific to BRCA1, BRCA2, and PALB2 in a large cohort of Taiwanese breast cancer patients through tumor-targeted sequencing." (PMID 38098088, 2023). "Among participants with a family history of breast cancer, PTVs in ATM, BRCA2, BRCA1, PALB2 and RAD50 were associated with an increased risk of breast cancer." (PMID 37790698, 2023). "Our study presents the one of the largest cohorts of breast cancer patients with BRCA1, BRCA2, and PALB2 mutations detected through tumor-only sequencing in Taiwan." (PMID 38098088, 2023). "Investigations indicated that PALB2 increasesconcurrently with the progression of breast cancer, which is rational due to its tumorsuppression role." (PMID 39430039, 2023). "The authors identified protein-truncating variants in BRCA1, BRCA2, CHEK2, PALB2 and ATM that were significantly associated with breast cancer risk." (PMID 37662839, 2023).
breast cancer (continued). "Four Fanconi anemia (FA) genes (BRCA1, BRCA2, PALB2 and RAD51C) are defined as breast cancer (BC) susceptibility genes." (PMID 37566130, 2023). "The American Society of Breast Surgeons recommends that genetic testing for BRCA1/2 and PALB2 be made available to every women with a personal history of breast cancer." (PMID 37084156, 2023). "The data presented here showed that the presence of familial breast cancer was more strongly associated with PV carrier status for ATM, BRCA1, BRCA2, CHEK2, and PALB2, in affected women (similar to previous studies)." (PMID 37084156, 2023). "(LCS=322) studied the role of BRCA2-interacting protein called partner and localizer of BRCA2 (PALB2) in breast cancer." (PMID 37476378, 2023). "Protein-truncating variants in BRCA2 and ATM were associated with a high risk of breast cancer, whereas PTVs in BRCA1 and PALB2 were associated with a high risk of estrogen receptor (ER)-negative disease." (PMID 37790698, 2023). "Carriers of PALB2, BARD1, RAD51C, RAD51D, ATM, and CHEK2 are at higher risk of breast cancer as well." (PMID 37458761, 2023). "Fanconi anemia is also brought on by germline homozygous loss of function (LoF) mutations of PALB2, like BRCA2, although heterozygous LoF mutations have been associated with hereditary breast cancer and pancreatic cancer." (PMID 37732318, 2023). "There was also hypermethylation of several important tumor suppressor genes, including high-penetrance (BRCA1) and moderate-penetrance (PALB2) breast cancer genes." (PMID 38131903, 2023). "For example, variants in PALB2 (Partner and Localizer of BRCA2) are associated with an estimated cumulative risk of breast cancer of 14%." (PMID 37182128, 2023). "Variants in key genes of HR, such as BRCA1, BRCA2, PALB2, BARD1, RAD51C, and RAD51D, which alter their function and/or their expression, have a significant association with breast cancer risk." (PMID 37372450, 2023). "By the time they are 70 years old, 33% of females who have a dangerous PALB2 gene alteration will have breast cancer." (PMID 36971312, 2023). "This stage mainly explored the mutations of breast cancer-associated genes, including BRCA1/2, PALB2, and so on, through sequencing technology and the risk of breast cancer." (PMID 37476378, 2023). "In our work, it was found that in almost 50% of cases of patients with breast cancer, chromosomal aberrations of PALB2 are observed." (PMID 37628606, 2023). "By comparing this finding to other breast cancer susceptibility genes recommended to be tested by the NCCN guideline, we found that the P/LP ratio in the PALB2 gene was the fourth most prevalent." (PMID 37686625, 2023). "Among patients and the established breast cancer susceptibility genes, PTVs in BRCA2 and ATM, followed by PALB2, and BRCA1, were the most prevalent." (PMID 37790698, 2023). "Here we examined the impact of two traditional markers of hereditary cancer risk (age at breast cancer diagnosis and family cancer history) on the risk of carrying a PV in the most commonly mutated breast cancer-risk genes: ATM, BRCA1, BRCA2, CHEK2, and PALB2." (PMID 37084156, 2023).
breast cancer (continued). "As anexample, there is a 92.5% promoter methylation and this hypermethylated state is accompanied byan increase in PALB2 expression level in plasma samples of breast cancer patients." (PMID 39430039, 2023). "Molecular and clinicopathological characteristics of breast cancer cases carrying PALB2 PVs/LPVs showed that all breast cancer tumors were invasive ductal carcinoma." (PMID 37169825, 2023). "Several studies have examined the potential risk modification of SNP/SNVs in familial breast cancers and, in particular, BRCA1, BRAC2, CHEK2, PALB2 and ATM mutation carriers." (PMID 36831687, 2023). "In particular, rare mutations in other breast cancer susceptibility genes, such as ATM and PALB2, are also likely to be associated with an increased risk of CBC." (PMID 36271417, 2022). "At least eight genes were found to be significantly associated with breast cancer risk: BRCA1 (MIM#113705), BRCA2 (MIM#600185), ATM (MIM#607585), BARD1 (MIM #601593), CHEK2 (MIM#604373), PALB2 (MIM#610355), RAD51C (MIM#602774), and RAD51D (MIM#602954)." (PMID 36139699, 2022). "Testing for PIK3CA mutation, germline BRCA1/2, PALB2 pathologic variant, homologous recombination deficiency (HRD), PD-L1 expression, and TMB is some of the latest developments to guide breast cancer treatment." (PMID 35884530, 2022). "In fact, the double CKO mice practically all succumb to neurodegeneration prior to any mammary tumor development, preventing any assessment of Atg7 in mammary tumorigenesis induced by inactivation of Palb2." (PMID 40396054, 2022). "Four recurrent loss-of-function variants were detected in 11 African-descended breast cancer cases, BRCA1:c.3331_3334delCAAG, BRCA1:c.211A>G, BRCA2:c.1389_1390delAG and PALB2:c.1671_1674delTATT." (PMID 35353237, 2022). "Breast cancer patients carrying BRCA1 or BRCA2 germline mutations have a mean onset age of 40 and 43 years, respectively, and patients carrying PALB2 mutations have a mean onset age of 53 years." (PMID 35494038, 2022). "Asian, Hispanic, and Native American women are at a lower risk of carrying breast cancer susceptibility genes, whereas in SA, BRCA1, PALB2 and RAD5IC genes are often responsible for breast cancer diagnosis." (PMID 36010323, 2022). "Germline mutations in PALB2, ATM, and CHEK2 are also associated with breast cancer risks as high as those associated with BRCA1/2 mutations and are often referred to as BRCA-like breast cancer." (PMID 35884530, 2022). "The promoters of several known tumor suppressor genes (e.g., ATM, BRCA1, and PALB2) were all hypermethylated in WTC exposed breast cancer cases compared to the unexposed group." (PMID 35564499, 2022). "The reversion mutations occurred only in 3 out of the 15 HRR genes: BRCA1 (3.8%), BRCA2 (3.5%) and PALB2 (2.0%) from 11 patients (6 breast cancers, 1 ovarian cancer, 1 pancreatic cancer, 1 lung cancer and 2 breast and ovarian dual cancers)." (PMID 35281878, 2022). "Four recurrent variants were discovered among unrelated African-descended breast cancer patients: BRCA1:c.3331_3334delCAAG, BRCA1:c.211A>G, BRCA2:c.1389_1390delAG, and PALB2:c.1671_1674delTATT." (PMID 35353237, 2022). "The current validation study successfully detected confirmed breast cancer susceptibility genes such as ATM, CHEK2, and PALB2." (PMID 35884425, 2022). "Approximately 5–10% of breast cancers are familial, resulting from inherited mutations in tumor suppressor genes such as BRCA1, BRCA2 and PALB2." (PMID 35404932, 2022). "Based on the estimated overall risk for breast cancer protein-truncating variants, ATM, BRCA1, BRCA2, CHEK2 and PALB2 were identified as the major cancer susceptibility genes in the study population." (PMID 36568162, 2022).